CXCR6 (C-X-C motif chemokine receptor 6)
Diseases named in the same sentence as CXCR6 in open-access papers (continued):
Sharing a sentence is not in itself a finding about the gene and the disease.
breast tumors (3 papers, 2019 to 2022). "This suggests that CXCR6 is potentially one of the chemokine receptors mediating pro-inflammatory microenvironment in Asian and Black breast tumors." (PMID 35754051, 2022). "Releasing T cells from primary breast tumors by breaking CXCR6-mediated retention led to enhanced protection against tumor metastasis in the distant lung." (PMID 33979626, 2021). "Molecular subtype analysis showed CXCR6 is significantly higher in triple negative and in HER2 enriched than in luminal A and B breast tumors." (PMID 35754051, 2022).
Cognitive impairment (3 papers, 2024 to 2025). Abnormal cognition is characterized by deficits in thinking, reasoning, or remembering. "Moreover, prior to the observation of CXCL16-CXCR6 mediated CD8 T cell infiltration in the mouse models, the CXCL16-CXCR6 axis-mediated CXCR6+ CD8 T cell homing to cerebrospinal fluid (CSF) followed by clonal expansion of the cells has been suggested in patients with cognitive impairment." (PMID 38355649, 2024).
Crohn disease (3 papers, 2013 to 2025). A gastrointestinal disorder characterized by chronic inflammation involving all layers of the intestinal wall, noncaseating granulomas affecting the intestinal wall and regional lymph nodes, and transmural fibrosis. "CXCR6 expression was similarly upregulated in inflamed mucosa of patients with Crohn’s disease." (PMID 23840334, 2013).
diabetes (3 papers, 2021 to 2022). "The diseases associated with CXCR6 include tumors, diabetes, respiratory diseases and immunodeficiency." (PMID 35116032, 2021). "In conclusion, our study provides transcriptomic data of an animal model with progressive diabetes-induced nephrotoxicity, and also demonstrates that C4b, CXCR6, CFD, and LIF are specific and sensitive biomarkers for early detection of diabetic nephropathy." (PMID 33922243, 2021). "We identified C4b, CFD, CXCR6, and LIF that were time dependently increased as diabetes progression as non-invasive biomarker candidates for diabetic nephropathy." (PMID 33922243, 2021).
end stage renal disease (3 papers, 2020 to 2025). "Thus our findings suggest that CXCL16/CXCR6 pathway may contribute to progression of end-stage renal diseases." (PMID 33922243, 2021).
eosinophilia (3 papers, 2019 to 2025). "We show that despite their decreased numbers, lung CXCR6-deficient ILC2 are even more activated cells producing large amount of type 2 cytokines that could drive eosinophilia." (PMID 31690060, 2019). "- CXCR6+ST2+ mTh2 cells facilitate eosinophilia in the lungs to reduce the fecundity in the lungs in re-infection." (PMID 33335529, 2020).
Hypertension (3 papers, 2020 to 2024). The presence of chronic increased pressure in the systemic arterial system. "We have recently demonstrated that CXCR6 is involved in kidney inflammation and fibrosis in animal models of angiotensin II-induced hypertension and obstructive nephropathy." (PMID 31924817, 2020). "In DOCA/salt model of hypertension, CXCR6 functions as a crucial mediator in recruiting myeloid fibroblasts, macrophages and T lymphocytes into the kidney resulting in kidney damage and fibrosis." (PMID 31924817, 2020). "In the present study, we utilized CXCR6 knockout mice to examine the role of CXCR6 in kidney damage in a salt-sensitive model of hypertension induced by DOCA/salt." (PMID 31924817, 2020). "For platelet CXCR6 (Figure 4Cii) they were median CXCR6-MFI (25th; 75th percentile) = 40.13 (30.28; 47.13) for w/o hypertension vs. 41.30 (32.20; 51.75) for w/hypertension." (PMID 36232370, 2022). "Hypertension seemingly did not affect platelet-CXCL16, serum sCXCL16 or CXCR6 surface expression on platelets." (PMID 36232370, 2022). "The presence or absence of hypertension did not influence platelet-CXCL16, platelet CXCR6 or serum levels of sCXCL16 (Figure 4Di–Diii)." (PMID 36232370, 2022).
ischemia (3 papers, 2018 to 2022). A hypoperfusion of the BLOOD through an organ or tissue caused by a PATHOLOGIC CONSTRICTION or obstruction of its BLOOD VESSELS, or an absence of BLOOD CIRCULATION. "In vivo experiments using CXCR6 knock-out mice have demonstrated that the disruption of the CXCL16/CXCR6 signaling had a cardioprotective effect against ischemia-reperfusion injury." (PMID 35625854, 2022). "Since we have shown that CXCL16 is neuroprotective in ischemia, and neuroinflammation plays a role in brain damage following ischemic insult, we considered the possibility that CXCL16, acting on CXCR6 expressed by microglia cells, might provide protective effects also modulating microglia phenotype." (PMID 30542347, 2018).
metabolic syndrome (3 papers, 2017 to 2022). A cluster of metabolic risk factors for CARDIOVASCULAR DISEASES and TYPE 2 DIABETES MELLITUS. "In addition, patients with metabolic syndrome reveal a higher percentage of circulating CXCR6 expressing platelets and CXCR6 expressing platelet-bound neutrophils, resulting in enhanced CXCR6/CXCL16-dependent adhesion to the dysfunctional arterial endothelium." (PMID 35784287, 2022). "Platelet-CXCL16 and CXCR6 expression did not alter with dyslipidemia, triglyceride, total cholesterol, or LDL levels, but higher (>median) plasma HDL levels corresponded with decreased platelet-CXCL16 and CXCR6." (PMID 36232370, 2022). "Contrary to our expectations, platelet-CXCL16, CXCR6 or serum sCXCL16 levels were not influenced by dyslipidemia to a significant extent or even by individual lipid (total cholesterol, triglyceride) or lipoprotein (LDL) profiles, all of which are major risk factors for ACS." (PMID 36232370, 2022). "Contrary to our expectations, in the current CAD-cohort, dyslipidemia, total cholesterol (TC), and triglyceride (TG) did not have any impact on platelet-CXCL16, CXCR6 or serum sCXCL16 levels." (PMID 36232370, 2022).
myocardial infarction (3 papers, 2022 to 2025). Gross necrosis of the myocardium, as a result of interruption of the blood supply to the area, as in coronary thrombosis. "Notably, CXCR6-deficient mice presented smaller myocardial infarct areas and better cardiac function than control mice did, indicating that CXCR6 deficiency inhibited monocyte infiltration and IFN-γ production, thereby alleviating myocardial I/R injury." (PMID 40535169, 2025). "In the case of CXCR6 (chemokine receptor for CXCL16), a recent publication has reviewed the contribution of chemokines and their receptors in myocardial infarction." (PMID 35625854, 2022).
pancreatic ductal adenocarcinoma (3 papers, 2021 to 2025). An infiltrating adenocarcinoma that arises from the epithelial cells of the pancreas. "In the early stage of pancreatic ductal adenocarcinoma, a higher expression of CXCR6 is associated with better overall survival." (PMID 33800554, 2021).
parasitemia (3 papers, 2021 to 2026). "Higher CXCR6+ CD127− Tr1 cell frequencies correlated with a lower probability of symptoms given parasitemia but were also associated with delayed parasite clearance among untreated, asymptomatic children." (PMID 41000872, 2025). "Importantly, the abundance of CXCR6+ CD127− Tr1 cells before and during infection correlated with future clinical outcomes, including the probability of symptoms given parasitemia and the duration of asymptomatic parasitemia." (PMID 41000872, 2025). "Interestingly, disruption of CXCR6 signaling did not affect control of the parasitemia, but significantly enhanced the survival of infected mice, associated with reduced inflammation and liver injury." (PMID 34614031, 2021).
prostate tumour (3 papers, 2019 to 2022). "In prostate tumours, inhibiting CXCR-6 expression can interrupt the differentiation of MSCs into CAFs and decrease the CXCL-12 secretion of CAFs via Erk and NF-κB signalling, and knockdown of CXCL16 in vitro also inhibits the formation of CAFs." (PMID 35869057, 2022). "Noteworthy is that stimulation of the CXCR6 pathway enhanced prostate tumor cell adhesion to endothelial cells and increased MMP expression." (PMID 32585812, 2020). "Prostate tumour cells show a high metastatic capacity, and metastasis to secondary sites (such as skeletal tissues) can be enhanced by MSC stimulation via CXCL16/CXCR6 signals." (PMID 35869057, 2022). "In addition, one of the most serious complications of prostate tumours is skeletal metastases, and the CXCL16/CXCR6 axis functions in chemoattraction to induce metastasis." (PMID 35869057, 2022).
pulmonary fibrosis (3 papers, 2022 to 2024). Chronic progressive interstitial lung disorder characterized by the replacement of the lung tissue by connective tissue, leading to progressive dyspnea, respiratory failure, or right heart failure. "In summary, our research revealed the increased secreation of CXCL16 from M2 macrophages in the context of bleomycin-induced pulmonary fibrosis, which was associated with the recruitment of CXCR6+ CD4 T cells." (PMID 38789926, 2024). "Here, we observed that the expression of CXCL16 and CXCR6 was elevated in the lung tissue of a pulmonary fibrosis model." (PMID 38789926, 2024). "It was also determined that CXCL16/CXCR6 contributed to pulmonary fibrosis in RA-ILD patients by up-regulating proliferation and collagen accumulation of human pulmonary fibroblasts (MRC-5 cells) mediated by the PI3K/AKT/FOXO3a pathway." (PMID 37833957, 2023). "It was determined that the serum level of sCXCL16 was significantly increased in RA-ILD patients, and CXCL16/CXCR6 could contribute to the severity of pulmonary fibrosis." (PMID 37833957, 2023). "Thus, there is already evidence that IL7R, LBH, and CXCR6 are important for understanding processes that promote pulmonary fibrosis, and LRRC39 and PLBD1 are additional targets for future studies." (PMID 35715807, 2022). "CXCR6 is a chemokine receptor that attracts T cells to the lungs and can promote the epithelial-mesenchymal transition in cell lines, an event that may be important to the progression of pulmonary fibrosis." (PMID 35715807, 2022). "The administration of bortezomib alleviated bleomycin-induced pulmonary fibrosis, accompanied by reduced ratio of M2-polarized macrophages and decreased accumulation of CD4 T cells expressing CXCR6." (PMID 38789926, 2024). "Five genes demonstrated concordant directions of effects between the ILA [IPF transcripts] and IPF scores (CXCR6, IL7R, LBH, LRRC39, PLBD1), suggesting these genes may represent important biologic processes in promoting the progression of pulmonary fibrosis." (PMID 35715807, 2022).
Anxiety (2 papers, 2022 to 2024). Intense feelings of nervousness, tension, or panic often arise in response to interpersonal stresses. "Expression of inflammatory markers, such as chemokine CXCR6, by meningeal γδ T cells, has been shown to influence anxiety in mice." (PMID 35444632, 2022). "After 2 weeks of injecting anti-CXCL16 neutralizing antibodies, we evaluated anxiety-related behaviours using the OFT and EPM tests to corroborate the possible roles of the CXCL16/CXCR6 axis in the recruitment of CD8+ T cells into the brain." (PMID 39386089, 2024). "Collectively, our study highlights that the brain glial-derived CXCL16, promoting CXCR6+CD8+ T accumulation, acts on hippocampal neurogenesis and anxiety via TNF-α production." (PMID 39386089, 2024). "Blocking CXCL16/CXCR6 axis alleviates HBV-mediated decreased hippocampal neurogenesis and anxiety-like behaviour." (PMID 39386089, 2024).
atopic dermatitis (2 papers, 2019 to 2023). "CXCR6/FYCO1 variant rs1386931:C > T was associated with atopic dermatitis." (PMID 30206357, 2019).
bladder cancer (2 papers, 2021 to 2024). "Specifically, in bladder cancer, low CXCR6 expression was associated with worse patient outcomes." (PMID 39588301, 2024). "We observed that CXCR6 expression was significantly reduced in bladder cancer tumors and correlated with tumor stage and grade." (PMID 39588301, 2024). "To explore the role of CXCR6 in cellular composition and molecular profiles, we analyzed scRNA-seq data from 9 bladder cancer samples (GSE222315)." (PMID 39588301, 2024). "First, we investigated the expression of CXCR6 in bladder cancer." (PMID 39588301, 2024). "The results revealed a significant positive correlation between CXCR6 expression and CD8A, effector T cell signature, and CD274 (PD-L1) in bladder cancer, suggesting that CXCR6 may hold potential as a predictive biomarker for immunotherapy response." (PMID 39588301, 2024).
chronic obstructive pulmonary disease (2 papers, 2017 to 2019). A chronic and progressive lung disorder characterized by the loss of elasticity of the bronchial tree and the air sacs, destruction of the air sacs wall, thickening of the bronchial wall, and mucous accumulation in the bronchial tree. "Within the lung, CXCR6 is more highly upregulated on human bronchoalveolar lavage (BAL)-derived and lung T-lymphocytes than those in the peripheral blood, and increased expression of CXCR6 on lung CD8+ T-lymphocytes correlates with disease severity in chronic obstructive pulmonary disease." (PMID 30899256, 2019).
Cirrhosis (2 papers, 2023 to 2024). A chronic disorder of the liver in which liver tissue becomes scarred and is partially replaced by regenerative nodules and fibrotic tissue resulting in loss of liver function. "In this study, we demonstrate that CXCR6+CD69+ CD8+ T cells are abundant in the ascites of patients with cirrhosis, exhibit a chronically activated bystander phenotype, and correlate with clinical parameters of disease severity." (PMID 38882602, 2024). "Subsequently, we asked whether the accumulation of CXCR6+CD69+ CD8+ T cells in the ascites compared with blood could also be induced by the ascites milieu in the peritoneal cavity of patients with cirrhosis." (PMID 38882602, 2024). "The results indicate that CXCR6+CD69+ CD8+ T cells in ascites are associated with disease severity and may contribute to inflammation in patients with decompensated cirrhosis, suggesting that targeted inhibition of this immune cell subset may be a viable therapeutic option." (PMID 38882602, 2024). "Indeed, we could demonstrate that frequencies of ascites CXCR6+CD69+ CD8+ T cells correlate with markers of disease severity in patients with decompensated cirrhosis, suggesting that these cells may play an important role in the disease pathogenesis." (PMID 38882602, 2024). "In particular, two landmark studies showed that anti-PD-1 treatment failed to reinvigorate CD8+ T cell tumor surveillance but paradoxically activated Cxcr6+ auto-aggressive CD8+TNF+PD-1+ T cells, which induce liver damage, cirrhosis, and HCC." (PMID 37586322, 2023).
encephalitis (2 papers, 2022 to 2025). An acute inflammatory process affecting the brain parenchyma. "Together, these data suggest a cell-intrinsic role for CXCR6 in promoting CD8+ TRM cell maintenance in the CNS after viral encephalitis, contributing to persistent microglial activation and synaptic elimination." (PMID 36153630, 2022). "In addition, Cxcr6−/− mice did not demonstrate any differences in weight loss, survival, or viral titers, suggesting that CXCR6 is not necessary for an effective immune response after WNV encephalitis, or trafficking of CD8+ T cells into the CNS parenchyma." (PMID 36153630, 2022). "Our study also did not assess potential recruitment of non-T cell populations expressing CXCR4 and CXCR6 during MuPyV encephalitis." (PMID 40581668, 2025).
fatty liver disease (2 papers, 2024 to 2026). A reversible condition wherein large vacuoles of triglyceride fat accumulate in liver cells via the process of steatosis. "For instance, it enhances the expression of CXCR6 in Group 3 innate lymphoid cells and promotes their liver homing mediated by the CXCL16/CXCR6 axis, leading to increased IL-22 secretion and reduced hepatic steatosis." (PMID 40990659, 2026).
fibrosis (2 papers, 2024 to 2025). the formation of excess fibrous connective tissue in an organ or tissue in a reparative or reactive process. "Through analysis of gene expression omnibus datasets and human fibrotic liver samples, we identified significant CXCR6 upregulation, subsequently validated in murine fibrosis models." (PMID 40822973, 2025). "Moreover, flow cytometry revealed increased expression levels of CD69 and CXCR6 in pulmonary CD4 T cells during fibrosis progression." (PMID 38789926, 2024).
gastrointestinal stromal tumor (2 papers, 2019 to 2021). "In gastrointestinal stromal tumor GIST-T1 and GIST882 cells, sCXCL16 reduces proliferation by activating CXCR6 and reducing ERK MAPK activity." (PMID 33800554, 2021). "In the same study, CXCR6+ ILC1-like cells were described in the peripheral and TILs of patients with gastrointestinal stromal tumors (GIST), although whether these cells are converted from classical NK cells is unknown." (PMID 31546818, 2019). "Also in gastrointestinal stromal tumor GIST-T1 and GIST882 cells, CXCR6-dependent sCXCL16 expression inhibits migration and EMT in cancer cells." (PMID 33800554, 2021).
heart failure (2 papers, 2018 to 2025). Inability of the heart to pump blood at an adequate rate to meet tissue metabolic requirements. "Soluble CXCL16 in the serum, when bound to CXCR6, plays an important role in pathological mechanisms following I/R injury in cardiac remodeling and heart failure development." (PMID 40535169, 2025). "CXCR6 is the specific receptor for CXCL16, and the CXCL16/CXCR6 axis plays an important role in pathological mechanisms following I/R injury in cardiac remodeling and heart failure development." (PMID 40535169, 2025).
hepatitis C (2 papers, 2022 to 2025). "The aggregated CD161hiCD8+T in hepatitis C livers highly expresses CXCR6, consistent with this study." (PMID 39799583, 2025). "High levels of CXCR6+ T cells (auto-aggressive) have been detected in the blood of hepatitis-C–infected patients compared with healthy controls, and > 60% of intrahepatic human T cells expressed CXCR6, including CD4, CD8, and CD56+ (NK) T cells." (PMID 35563807, 2022).
inflammatory bowel disease (2 papers, 2020 to 2022). A spectrum of small and large bowel inflammatory diseases of unknown etiology. "Among DP8α T cells, there were F. prau-specific T cells co-expressing CCR6 and CXCR6, decreased in inflammatory bowel disease (IBD) patients." (PMID 32099648, 2020).
kidney damage (2 papers, 2020 to 2025). "Notably, T cells in kidney biopsies from PyV-associated nephropathy patients express CXCR6 and transcriptional analysis shows significant upregulation of CXCR6 and CXCL16." (PMID 40043065, 2025). "To examine the role of CXCR6 in the development of kidney damage, we stained the kidney sections with periodic acid-Schiff (PAS)." (PMID 31924817, 2020).
metastatic melanoma (2 papers, 2020 to 2021). A melanoma that has spread from its primary site to another anatomic site. "Moving to potential future biomarkers, increased frequency of expression of TIM‐3 and CXCR6+ on CD4+ T cells in metastatic melanoma patients with PD was confirmed." (PMID 34129290, 2021).
metastatic tumor (2 papers, 2011 to 2024). "Specifically, CXCR6, CCR2, CCR4, IL2Ra were both deleted and had lower gene expression in the primary versus metastatic tumors." (PMID 22194851, 2011).